SP1 (Sp1 transcription factor)
Description:
Transcription factor that can activate or repress transcription in response to physiological and pathological stimuli. Binds with high affinity to GC-rich motifs and regulates the expression of a large number of genes involved in a variety of processes such as cell growth, apoptosis, differentiation and immune responses. Highly regulated by post-translational modifications (phosphorylations, sumoylation, proteolytic cleavage, glycosylation and acetylation). Also binds the PDGFR-alpha G-box promoter. May have a role in modulating the cellular response to DNA damage. Implicated in chromatin remodeling. Plays an essential role in the regulation of FE65 gene expression. In complex with ATF7IP, maintains telomerase activity in cancer cells by inducing TERT and TERC gene expression. Isoform 3 is a stronger activator of transcription than isoform 1. Positively regulates the transcription of the core clock component BMAL1. Plays a role in the recruitment of SMARCA4/BRG1 on the c-FOS promoter. Plays a role in protecting cells against oxidative stress following brain injury by regulating the expression of RNF112 (By similarity).
Tractability: PROTAC: UniProt records ubiquitination sites on it; ubiquitination databases record sites on it; its protein half-life has been measured; a small molecule that binds it is known.
Target class: Transcription factor
Gene: Protein-coding gene on chromosome 12 (53,380,176 to 53,416,446, forward strand). Ensembl gene ENSG00000185591.
Subcellular location: Nucleus; Cytoplasm
Subcellular location (Human Protein Atlas): Nucleoplasm
Pathways (Reactome):
Signal Transduction: Estrogen-dependent gene expression; SMAD2/SMAD3:SMAD4 heterotrimer regulates transcription; TGFBR3 expression
Cell-Cell communication: Positive Regulation of CDH1 Gene Transcription; Regulation of CDH11 gene transcription
Cellular responses to stimuli: NFE2L2 regulating tumorigenic genes; Oncogene Induced Senescence
Metabolism: Activation of gene expression by SREBF (SREBP); PPARA activates gene expression
Disease: SARS-CoV-1 targets host intracellular signalling and regulatory pathways
Gene expression (Transcription): RNA polymerase II transcribes snRNA genes
Gene Ontology:
Molecular function: DNA binding; DNA-binding transcription activator activity, RNA polymerase II-specific; DNA-binding transcription factor activity; DNA-binding transcription factor activity, RNA polymerase II-specific; double-stranded DNA binding; histone deacetylase binding; identical protein binding; molecular adaptor activity; protein binding; protein homodimerization activity; RNA polymerase II cis-regulatory region sequence-specific DNA binding; RNA polymerase II transcription regulatory region sequence-specific DNA binding; sequence-specific DNA binding; sequence-specific double-stranded DNA binding; transcription cis-regulatory region binding; transcription coregulator binding; bHLH transcription factor binding; RNA polymerase II-specific DNA-binding transcription factor binding; histone acetyltransferase binding
Biological process: host-mediated activation of viral transcription; positive regulation of amyloid-beta formation; positive regulation of angiogenesis; positive regulation of apoptotic signaling pathway; positive regulation of blood vessel endothelial cell migration; positive regulation of DNA-templated transcription; positive regulation of gene expression; positive regulation of hydrogen sulfide biosynthetic process; positive regulation of transcription by RNA polymerase II; positive regulation of vascular endothelial cell proliferation; regulation of DNA-templated transcription; regulation of transcription by RNA polymerase II; response to hydroperoxide; cellular response to estrogen stimulus; cellular response to insulin stimulus; cellular response to wortmannin; cellular response to zinc ion starvation
Cellular component: chromatin; euchromatin; nucleoplasm; nucleus; transcription repressor complex; protein-DNA complex; cytoplasm
Genetic constraint (gnomAD): Loss-of-function variants: 6 observed, 70.1 expected, observed/expected ratio (o/e) 0.0856, 90% interval 0.046 to 0.17. The upper end of that interval is the gene's LOEUF score, 0.17, which puts it in group 1 of 6, group 1 being the genes least tolerant of losing a copy. Missense variants: 848 observed, 1,019.2 expected, observed/expected ratio (o/e) 0.83, 90% interval 0.79 to 0.88. Synonymous variants: 417 observed, 382.93 expected, observed/expected ratio (o/e) 1.09, 90% interval 1 to 1.18.
Homologues: Orthologues: chimpanzee SP1 (100% identical), macaque SP1 (99% identical), rabbit SP1 (98% identical), dog SP1 (97% identical), guinea pig SP1 (97% identical), pig SP1 (96% identical), rat Sp1 (96% identical), mouse Sp1 (95% identical), tropical clawed frog sp1 (65% identical), zebrafish sp1 (39% identical), Drosophila melanogaster Spps (31% identical), Drosophila melanogaster pad (22% identical). Paralogues in human: SP4 (41% identical), SP3 (37% identical), SP2 (27% identical).
Diseases named in the same sentence as SP1 in open-access papers:
SP1 is named in the same sentence as 365 diseases in open-access papers, as found by Europe PMC text mining. Sharing a sentence is not in itself a finding about the gene and the disease. The quoted sentences say what the papers report.
breast carcinoma (231 papers, 1984 to 2025). "Numerous studies have reported high expression levels for SPHK1 and SP1 in breast cancer tissues, which are closely associated with poor prognosis and lower survival rates." (PMID 40002245, 2025). "Overexpression of SP1 is frequently associated with a poor prognosis in malignancies such as breast carcinoma, as it enhances tumor development, invasiveness, and chemoresistance." (PMID 41155227, 2025). "The regulation of Sp1 ubiquitination has been linked to the advancement of various cancers such as gastric cancer (GC), melanoma, lung cancer, breast cancer, colorectal cancer, acute myeloid leukemia, and more." (PMID 39228402, 2024). "In breast cancer, Sp1 is activated by GDNF via AKT, causing Sp1 to activate, in turn, the ST3GAL1 promoter." (PMID 39614261, 2024). "Specificity protein 1 (Sp1) is a transcription factor overexpressed in breast cancer, and its expression is negatively associated with BC TNM stage and metastasis status via transcriptionally activating aplasia Ras homologue member I (ARHI)." (PMID 37692513, 2023). "A poor prognosis is associated with high expression of Sp1 in some types of cancer, such as glioblastoma, lung cancer and breast cancer." (PMID 37147632, 2023). "The SP1 transcription factor is linked to breast cancer and Huntington's disease, acting together with ATF7IP to maintain telomerase activity via inducing the expression of TERT and TERC." (PMID 32157780, 2020). "Supporting this observation, the TCGA dataset analysis showed that the breast cancer patients with high expression levels of Sp1 and TMBIM6 increased the risk of cancer mortality." (PMID 31336725, 2019). "The analysis showed that the risk of breast cancer mortality increased with high expression of Sp1 and TMBIM6." (PMID 31336725, 2019). "The associations of E2F1, SP1 and estrogen receptor in breast cancer have been described previously." (PMID 27888801, 2017). "Analysis indicated that high SP1 mRNA expression was associated with distant recurrence of breast cancer (P = 0.023)." (PMID 27545642, 2016). "The expression of Sp1 in breast cancer tissues is positively associated with TNM stage, tumor invasion and lymph node metastasis." (PMID 23403540, 2013). "In addition, immunofluorescence assay showed that ZN444B inhibited the association of HDAC1 with Sp1 in breast cancer cells." (PMID 39010083, 2024). "In terms of mechanisms, both immunofluorescence assay and western blotting assay validated that ursolic acid treatment significantly attenuated the expression levels of glycolysis-associated proteins (LDH-A and c-Myc) whereas increasing SP1 and Cav-1 expression levels in mammary tumor tissues." (PMID 34568078, 2021). "Syk has been shown to regulate Sp1 transcription factor activity in breast cancer cells; therefore, loss of syk may predispose breast epithelial cells to ErbB2-mediated downregulation of α2 integrin, resulting in a further step along the progression pathway." (PMID 22203845, 2011). "Ligand-dependent induction of luciferase activity in breast cancer cells transfected with pSp13-luc was also induced by E2 and structurally-diverse estrogenic endocrine disruptors and responses varied with respect to ERα (wild = type/mutations) and expression of Sp1, Sp3 and Sp4." (PMID 39858066, 2025). "Furthermore, our in-silico knockout in breast cancer and paired primary and metastatic site mouse scRNA-seq datasets showed that a loss of SP1 in high metastatic cells could reverse the fates to a low metastatic state." (PMID 39748426, 2025). "It was also observed that vitamin D receptor-interacting protein 150 (DRIP150) coactivated ERα/Sp1 in breast cancer cells." (PMID 39858066, 2025).
breast carcinoma (continued). "Based on this analysis, the bcl3 promoter was selected as a model SP1-enriched promoter, as it exhibited a higher QGRS score and the bcl3 gene is strongly associated with breast cancer." (PMID 40884402, 2025). "Of note is the group of genes SP1, MYC, HEY2, E2F1, E2F2, and HES1, which are known to be associated with the KEGG breast cancer functional pathway." (PMID 40724805, 2025). "Accordingly, we selected the Bcl3 promoter as our experimental model among the 14 SP1-enriched, G4-containing candidates, based on its high G4-forming potential (G-score = 42; ranked 3rd) and its established relevance to breast cancer." (PMID 40884402, 2025). "As a proof-of-principle for prioritising TFs as novel therapeutic targets, we examined our breast cancer scRNA-seq and perturbed SP1 in silico." (PMID 39748426, 2025). "Depleting TBX2, Sp1 or CoREST members resulted in the de-repression of NDRG1 which was accompanied by reduced breast cancer cell viability and colony-forming ability." (PMID 39912718, 2025). "Transcription factors such as specificity protein 1 (Sp1) and AP-2 regulate SOD2 transcription, and silencing of AP-2 by hypermethylation has been linked to MnSOD upregulation in aggressive breast cancer." (PMID 40722952, 2025). "Sp1 is required by PR for transcriptional activation of multiple target genes including cell cycle regulators and is a marker of poor prognosis in breast cancer." (PMID 40105700, 2025). "To explore this, we identified SP1-enriched promoters in the MCF-7 human breast cancer cell line, in which SP1 plays a pivotal role in cancer-related processes." (PMID 40884402, 2025). "Studies have revealed that SP1 is involved in the regulation of Timeless expression in breast cancer." (PMID 38354174, 2024). "Our findings are interpreted to show that SP-1-303 exhibits toxicity preferentially against ER+ breast cancer cells when compared to normal breast epithelial cells (MCF10A) and triple-negative breast cancer cells (HCC1937 and MDA-MB-231)." (PMID 39008483, 2024). "Combined targeting of class I HDACs and ATM by SP-1-303 offers a promising therapeutic approach for treating ER+ breast cancers and supports further preclinical evaluation." (PMID 39008483, 2024). "Studies have indicated that SP1 expression is elevated in some cancer types, including glioblastoma, lung cancer, breast cancer, and cervical cancer, and that these conditions are linked to a poor prognosis." (PMID 39056681, 2024). "A recent report revealed that Timeless interacts with SP1/c-Jun to promote c-Jun-mediated transcriptional induction of miR-5188, leading to the promotion of malignancy of breast cancer." (PMID 38354174, 2024). "Previous studies have reported that Sp1 is overexpressed in several cancers, including gastric cancer, colon cancer, lung cancer and breast cancer, and is positively correlated with tumour progression." (PMID 37147632, 2023). "Similar results were observed in RKO and SW480 cells, indicating that PD-L1 is regulated by NR4A1/Sp1 in colon cancer cells as previously observed in human and mouse breast cancer cells and NR4A1 antagonists decrease expression of this checkpoint gene product." (PMID 37847301, 2023). "We obtained ChIP-seq data of the candidate transcription factors FOSB (ENCSR569XNP), ZNF302 (ENCFF037UPH), SP1 (ENCFF072FPF), ELK1 (ENCFF123KER), and FOXF2 (ENCFF008ABX) in a breast cancer cell line MCF-7 from ENCODE." (PMID 37173692, 2023). "Together, our data supported the notion that SGCE promotes breast cancer stemness partially by interacted with Sp1 to enhance the transcription of FGF-BP1." (PMID 37838174, 2023). "Our previous study revealed that TIM interacts with specificity protein 1 (Sp1) and upregulates sphingolipid synthesis, which contributes to breast cancer growth and activates mitochondrial respiration." (PMID 37340461, 2023).
breast carcinoma (continued). "In this study, we collected breast cancer cells at 1st, 2nd, 3rd, and 4th which were numbered SP1, SP2, SP3 and SP4 in the spheroid formation experiment." (PMID 38037058, 2023). "Previous studies in breast cancer cells show that NR4A1 acts as a cofactor of Sp1-mediated expression of PD-L1, and our results confirm a similar pathway in colon cancer cells." (PMID 37847301, 2023). "Activation of CAV1 by SP1 downregulates glycolytic metabolism and damages mitochondrial function in breast cancer cells." (PMID 36077352, 2022). "Another study confirmed the direct interaction between VEGFA and SP1 in breast cancer cells by Chromatin Immunoprecipitation (ChIP) experiment." (PMID 36467048, 2022). "Prior research has highlighted that miR-212-3p inhibits both protein and mRNA levels of SP1 in breast cancer cells." (PMID 35150479, 2022). "STAT6 interacted with SP1 and increased the expression of p21 and p27 in promoting breast cancer cell proliferation." (PMID 35600336, 2022). "In terms of its downstream mechanism, miR-212-3p was previously demonstrated to target specificity protein 1 (SP1) in breast cancer." (PMID 35150479, 2022). "The clear oncogenic role of SP1 has been observed in multiple diseases, such as ovarian cancer, prostate cancer, breast cancer, Ewing sarcoma, and OS." (PMID 35590288, 2022). "GS results in the O-linked N-acetylglucosaminylation (O-GlcNAcylation) of specificity protein 1 (Sp1) for the induction of the SREBP-1/ACC1 pathway, which increases lipogenesis and lipid droplet accumulation in liver and breast cancer." (PMID 35912181, 2022). "In estrogen receptor-positive breast cancer, the most prevalent type of breast cancer, SP1 interacts with the circadian gene TIMELESS (TIM) to increase alkaline ceramidase 2 (ACER2) and enhance mitochondrial respiration." (PMID 36077352, 2022). "Further investigations revealed that ursolic acid suppressed breast cancer growth and lung metastasis by impairing glycolytic metabolism via inducing the SP1/Cav-1 pathway." (PMID 34568078, 2021). "Recently it has been demonstrated that Sp1 interacts with the epigenetic enzyme KMT2A in the breast cancer cell line MCF7 cells." (PMID 34899171, 2021). "According to CPTAC dataset from UALCAN, protein expression of SP1 was higher in breast cancer, ovarian cancer, colon cancer and lung cancer, compared with their corresponding normal tissues, and the difference was significant." (PMID 34257529, 2021). "In contrast, tumor-suppressor miRNAs such as miRNA-539 prevent breast cancer proliferation via specificity protein 1 (SP1) inhibition." (PMID 33670518, 2021). "Altogether, ursolic acid impairs the glycolytic metabolism of breast cancer cells by activating SP1/Cav-1 signaling." (PMID 34568078, 2021). "TIM can regulate sphingolipid metabolism and promote tumor cell growth through Sp1/ACER2/S1P axis in breast cancer." (PMID 34490127, 2021). "In breast cancer cells, Jianguo Hu group reported that SP1-induced lncRNA AGAP2-AS1 enhanced the chemoresistance of breast cancer by epigenetic regulation of MyD8818." (PMID 33431838, 2021). "HDAC5 expression was also elevated in estrogen-independent breast cancer cells and induced tamoxifen resistance via the miR-125a-5p/specificity protein 1 (Sp1)/survivin axis." (PMID 34178647, 2021). "A total of six articles, including 1,304 patients with pancreatic cancer, cholangiocarcinoma, breast cancer, osteosarcomas, esophageal cancer or gastric cancer, investigated SP1 expression in tissues." (PMID 34257529, 2021). "Taken together, ursolic acid hinders breast cancer growth and metastasis in vivo by suppressing glycolytic metabolism via activating SP1/Cav-1 signaling." (PMID 34568078, 2021). "Many tumors show increased SP1 expression, including breast cancer, gastric cancer, lung cancer and pancreatic cancer, compared with adjacent healthy tissues." (PMID 34257529, 2021).